INHBA (inhibin subunit beta A)
Diseases named in the same sentence as INHBA in open-access papers (continued):
Sharing a sentence is not in itself a finding about the gene and the disease.
INHBA also shares sentences with these, for which no sentence is quoted: prostate carcinoma (6 papers); head and neck squamous cell carcinoma (3); adenocarcinoma (2); asthma (2); head and neck cancer (2); invasive ductal breast carcinoma (2); metastatic tumors (2); Right ventricular hypertrophy (2); Allergy (1); Bardet-Biedl syndrome (1); Barrett esophagus (1); basal cell carcinoma (1); bladder urothelial carcinoma (1); bone metastasis (1); colorectal) (1); ductal carcinoma in situ (1); glioblastoma (1); Hypertension (1); hypogonadism (1); idiopathic pulmonary fibrosis (1); immune dysfunction (1); Infertility (1); juvenile idiopathic arthritis (1); leukemia (1); liver fibrosis (1); Lymphatic Metastasis (1); metastasis (1); metastatic colorectal cancer (1); Noonan syndrome (1); oral squamous cell carcinoma (1).
A further 17 diseases each share a sentence with INHBA in 1 paper.